NOX1 (NADPH oxidase 1)
Diseases named in the same sentence as NOX1 in open-access papers (continued):
Sharing a sentence is not in itself a finding about the gene and the disease.
infection (continued). "Overall, these findings indicate that Nox1 is a strong suppressor of airways and lung inflammation and oxidative stress that occurs during the early stages of the infection phase, particularly when the innate immune system is maximally active." (PMID 23577160, 2013). "In addition, the Nox1 and Nox2 complexes have a crucial role in determining the differences between different virulence determinants including appressoria and infection peg formation." (PMID 36352882, 2022). "To examine whether this pathway alters LS burden in vivo, and to evaluate the impact of complete NOX1 knockout, we compared infection in WT and NOX1−/− C57Bl/6 mice." (PMID 31065106, 2020). "Furthermore, a greater percentage of conventional and interstitial dendritic cells from Nox1*/Y draining lymph nodes expressed the co-stimulatory ligand CD40 within 6 days post-infection." (PMID 26910342, 2016). "However, 3 days after infection, the cellular infiltrate in WT mice increased by ∼10 fold from basal levels, which was similar in Nox1−/y mice." (PMID 23577160, 2013). "We assessed mRNA levels of several pro-inflammatory and anti-inflammatory (IL-10) cytokines and chemokines in the lungs of naïve and HkX-31 infected WT and Nox1−/y mice at early (i.e. Day 3) and later (i.e. Day 7) stages of the infection phase with quantitative real time PCR." (PMID 23577160, 2013). "In addition, the protective role of NOX1 activity have been shown to limit inflammatory response and lung tissue damage exerted by influenza A at early stage of infection in mice even though the NOX1 activity in different circumstances, such as hyperoxia, can cause tissue damage." (PMID 37251385, 2023). "This implied that augmented OS induced by NOX1 may contribute to the oxidative damage of cellular membranes and macromolecules, and thus led to cellular apoptosis and death by dysregulation of miRNAs in the acute infection." (PMID 35360170, 2022). "The expression of NADPH oxidase 1 (nox1) gene, which encodes a membrane-bound pro-oxidant enzyme that catalyzes superoxide synthesis, was significantly down-regulated 1 h post-infection with A. salmonicida compared to the non-treated cells and the bacterin-exposed macrophages." (PMID 31231379, 2019). "Male WT and Nox1-deficient (Nox1−/y) mice were infected with the moderately pathogenic HkX-31 (H3N2, 1×104 PFU) influenza A virus for analysis of bodyweight, airways inflammation, oxidative stress, viral titre, lung histopathology, and cytokine/chemokine expression at 3 and 7 days post infection." (PMID 23577160, 2013). "Citrobacter rodentium anaerobically reduces NOX1 generated H2O2 via cytochrome c peroxidase, to outcompete resident commensals and attach to colonic epithelium in mice during early infection." (PMID 38307490, 2024). "During infection, reactive oxygen species (ROS) are produced at the epithelial interface by the host NADPH oxidase NOX1 as a defense mechanism against invading pathogens." (PMID 38078767, 2024). "During an infection process, DUOX2 activity can be modulated by another intestinal epithelium NADPH oxidase, namely NADPH Oxidase 1 (NOX1)." (PMID 35203499, 2022). "In contrast, blocking negative regulators of this pathway, NOX1 and TFR1, leads to an increase in liver stage infection." (PMID 31065106, 2020). "These in vivo data suggest a role for Nox1 and APE1 in the response to infection of human stomach with H. pylori." (PMID 26761793, 2016). "While Mabs S did not significantly modulate the expression of NOX1 and DUOX1 oxidases, we measured a significant increase in DUOX1 expression upon Mabs R infection, suggesting enhanced ROS production by this variant." (PMID 37619220, 2023). "Infection of bone marrow-derived macrophages (BMDM) with S. aureus revealed that NADPH oxidase 2 (NOX2-) deficient, but not NOX1- or NOX4-deficient, BMDM failed to clear intracellular S. aureus." (PMID 33868252, 2021).
infection (continued). "Therefore, VopL deploys a general mechanism to cripple the defenses of the host cell: it paralyzes the actin cytoskeleton, preventing assembly of both NOX1 and NOX2 complex, thereby inhibiting the generation of ROS during infection." (PMID 28640881, 2017). "As DPI is not a specific inhibitor of Nox1, we used siRNA-mediated suppression of Nox1 to show a comparable decrease in luminol oxidation following infection with H. pylori ROS." (PMID 26761793, 2016). "Furthermore, expression of several key host defense genes, including cytokines (TNFα and IL6) and bactericidal molecules, such as defensin-4 (NP4), NOS2, NOX1 and ICAM1, peaked only at 8 and/or 12 weeks post-infection." (PMID 22645653, 2011). "The present study shows that Nox1 oxidase critically inhibits the early burst in lung pro-inflammatory cytokine expression, inflammation and oxidative stress caused by influenza A virus infection and therefore, as opposed to the Nox2 oxidase, Nox1 is a protective mechanism against such infections." (PMID 23577160, 2013). "Infection of Cybb-/- and Nox1-/- mice showed that the LPS-induced S. Tm bloom does not solely depend on CYBB or NOX1, suggesting potential redundancy in ROS generation pathways." (PMID 40113753, 2025).
cardiovascular disease (17 papers, 2014 to 2024). "Increased NOX1 expression in the plaques of patients with cardiovascular disorders has been found, while the deletion of NOX1 reduces lesion area in the Apoe-/- mouse model of AS." (PMID 38671747, 2024). "While Nox1, Nox2, and Nox4 have been well characterized in models of cardiovascular disease, little is known about Nox5." (PMID 30334629, 2019). "Thus, rac1 pharmacological inhibition resulting in the decreased NOX1 or NOX2 activity may restore human vascular smooth muscle function in a certain cardiovascular disease of humans." (PMID 34440716, 2021). "Angiotensin II regulates the onset and progression of cardiovascular diseases by increasing NADPH oxidase activity and leading to upregulation of vascular NOX1 and NOX2, which are important in redox-mediated hypertension in various cardiovascular diseases." (PMID 37891892, 2023). "Setanaxib (GKT137831), a preferential direct inhibitor of NOX1 and NOX4, can delay or prevent the progression of many cardiovascular disorders by inhibiting reactive oxygen species (ROS) generation." (PMID 35444554, 2022). "Previous studies denoted that the NOX1, NOX2, and NOX4 enzymes are expressed in cardiovascular tissues and not only participate in normal vascular and cardiac function but also contribute to the development of cardiovascular disease." (PMID 29156835, 2017).
adenocarcinoma (7 papers, 2016 to 2024). A common cancer characterized by the presence of malignant glandular cells. "It has been reported that integrins were associated with NOX activation and ROS production, and that type IV collagen mediated the activation of NOX1 through their binding to α2β1 integrin in the human adenocarcinoma cell line." (PMID 33498253, 2021). "We also demonstrate high level NOX1 expression for the first time in adenocarcinomas of the small intestine." (PMID 32428030, 2020). "In that respect, an earlier study was able to show that the induction of the Nrf2 pathway in NOX1-expressing adenocarcinoma A549 cells augments HIF-1α signaling." (PMID 27286880, 2016). "In adenocarcinoma cells following intermittent hypoxia, NADPH oxidase 1 (NOX1)-induced ROS increases NRF2/TRX1 levels and thereby increase HIF-1α protein levels." (PMID 38424190, 2024). "Results showed that both NOX1 and p67phox expression are either absent or extremely low in the normal prostate tissue in non-transgenic mice, but their expression increased with the disease progression from PIN to adenocarcinoma in TRAMP prostate tissue." (PMID 26979487, 2016).
inflammation (7 papers, 2010 to 2025). Aberrant reaction of the microcirculation characterized by movement of fluid and leukocytes from the blood into extravascular tissues. "Herein, we found that Nox1 deficiency in SMCs reduced the immune cells, and expressions of the proinflammatory cytokines in aortas and ameliorating vascular inflammation." (PMID 39721498, 2025). "NOX1 and NOX4 have been shown to be associated with inflammation related diseases in recent reports." (PMID 36009258, 2022). "NOXO1 is an organiser protein that activates NADPH oxidase (NOX1) and increased Noxo1 expression may be a marker for oxidative stress during lung inflammation." (PMID 20184723, 2010). "Sources of reactive oxygen species from micro-SPM in the lung are NOX1 and NOX2, driven by pulmonary inflammation, while oxidative stress from nano-SPM in the heart is mediated by protein kinase C-dependent p47phox phosphorylation, leading to NOX2 activation in infiltrated monocytes." (PMID 40319735, 2025). "Whether NOX1 and NOX4 are involved in the TNF-α-induced lung inflammation needs to be investigated in the future." (PMID 23671702, 2013).
nephropathy (5 papers, 2011 to 2025). A nonspecific term referring to disease or damage of the kidneys. "NOX1 is associated with to various renal disorders, including hyperlipidemic renal injury, diabetic nephropathy, and ischemia-reperfusion injury." (PMID 40621077, 2025). "Although many studies have linked NOX1 to various renal diseases, its role in HN has rarely been discussed." (PMID 40621077, 2025). "Although NOX1 can also be detected in renal cells, including glomerular endothelial cells, podocytes, and tubulointerstitial cells, the dominant NOX isoform in the kidney and the primary source of reactive oxygen species (ROS) in renal disease is widely recognized as NOX4." (PMID 41154471, 2025).
colorectal (4 papers, 2015 to 2020). "NOX1 levels were also correlated with the levels of α-fetoprotein (AFP), a major serum protein produced by the fetal liver which is repressed upon hepatocyte maturation but reactivated in liver malignancies." (PMID 25806803, 2015).
neurodegenerative disease (4 papers, 2020 to 2023). A disorder of the central nervous system characterized by gradual and progressive loss of neural tissue and neurologic function. "Moreover, it has been shown that NoxO1, potentially through Nox1, promotes peroxynitrite formation, which contributes to the development of degenerative diseases like COPD." (PMID 32949971, 2020). "In particular, NADPH oxidase 1 (NOX1) and NADPH oxidase 2 (NOX2) enzymes have been also described as key contributors in the development of neuropsychiatric and neurodegenerative diseases." (PMID 33917814, 2021). "NOX1, 2, and 4 are the main NOX subtypes expressed in neurons, while the role of NOX2 and NOX4 in neurodegenerative diseases has been relatively well studied." (PMID 33644049, 2021). "NOX1, NOX2, and NOX4 are the major subtypes of NOX in the central system that play a major role in brain injury and neurodegenerative diseases." (PMID 33644049, 2021).
neurological diseases (3 papers, 2022). "NOX2 is the main source of ROS in phagocytes; however, NOX1-and NOX4-dependent ROS productions may occur in microglia of different neurological diseases." (PMID 36278207, 2022).
vasculopathies (3 papers, 2019 to 2025). "NAD (P) H oxidases are the major sources of intracellular ROS production in Hcy-induced endothelial cells and NAD (P) H oxidases consist of multiple subunits, containing membrane-associated Nox1–4 and p22phox subunits, with Nox4 playing the key role in vasculopathies." (PMID 30315526, 2019). "We subsequently speculated that Nox1-regulated PAK1 is involved in vascular disorders." (PMID 39721498, 2025).
cardiac disease (2 papers, 2022 to 2023). "Given its high expression in monocytes of humans with DD, NOX1 may represent a potential target to mitigate heart disease associated with DD." (PMID 34849611, 2022). "NOX1 could also mediate metabolic heart disease through regulation of vascular smooth muscle cells (VSMCs)." (PMID 34849611, 2022).
metabolic disease (2 papers, 2022 to 2023). A congenital disorder (due to inherited enzyme abnormality) or acquired (due to failure of a metabolically important organ) disorder resulting from an abnormal metabolic process. "NOX1 is expressed in vascular and immune cells and has been implicated in the vascular pathology of metabolic disease." (PMID 34849611, 2022). "NOX1 mediates endothelial activation and contributes to myocardial inflammation and remodelling in metabolic disease in mice." (PMID 34849611, 2022). "In a mouse model of metabolic disease, we demonstrate that NOX1 is mandatory for cardiac endothelial activation and myocardial remodelling." (PMID 34849611, 2022). "To test the role of NOX1 in metabolic heart disease, we induced metabolic disease in WT and KO mice by HFHS and a single low-dose STZ injection (75 mg/kg i.p.)." (PMID 34849611, 2022). "We found increased nitrotyrosinylation at 44 weeks in the hearts of WT, but not of NOX1-deficient metabolic disease mice." (PMID 34849611, 2022). "In summary, HFHS/STZ led to a metabolic disease phenotype in mice, independently of NOX1." (PMID 34849611, 2022). "NOX1 is upregulated in peripheral monocytes in patients with DD and its genetic deletion prevents cardiac endothelial activation, inflammation, and remodelling in metabolic disease in mice." (PMID 34849611, 2022). "Whether NOX1 is upregulated and contributes to CD11b+CD64+ or other immune cell function in metabolic disease remains to be determined." (PMID 34849611, 2022).
retinopathies (2 papers, 2015 to 2024). "Studies in a mouse model have demonstrated that Nox1 knockout, but not Nox2 or Nox4 knockout, protects the retina against oxygen-induced retinopathy and identifies microglia as the source of hypoxia-induced ROS generation and neovascularization." (PMID 38612560, 2024). "NOX1/4 enzyme inhibition with GKT137831 has potent anti-inflammatory effects in the retina, indicating its potential as a treatment for a variety of vision-threatening retinopathies." (PMID 26219952, 2015).
bacterial infection (1 paper, 2016). "APE1 is a negative regulator of oxidative stress in the gastrointestinal epithelium during bacterial infection by modulating Rac1 and Nox1." (PMID 26761793, 2016). "Together, these data support the concept that through its molecular interactions with Rac1, APE1 provides negative feedback on Nox1 and oxidative responses in the gastrointestinal epithelium during bacterial infection." (PMID 26761793, 2016).
gastrointestinal disease (1 paper, 2021). A disease that occurs in the gastrointestinal system, excluding the hepatobiliary system. "Particularly, loss of function and excessive activity of enzymes producing reactive oxygen species DUOX2 and NOX1 have been suggested to contribute to gastrointestinal disease progression." (PMID 33930606, 2021).
psychiatric diseases (1 paper, 2025). "There are recent studies investigating the role of NOX1 in psychiatric diseases and animal models of psychiatric diseases." (PMID 40619989, 2025).
NOX1 also shares sentences with these, for which no sentence is quoted: heart failure (5 papers); arteriosclerosis (3); chronic granulomatous disease (3); acute respiratory distress syndrome (2); adenoma (2); anaplastic thyroid cancers (2); cardiac ischemia (2); cervical squamous cell carcinoma (2); colorectal tumor (2); Hyperoxaluria (2); immune diseases (2); lung adenocarcinoma (2); neuroblastoma (2); papillary carcinoma (2); type 1 diabetes (2); acute myeloid leukemia (1); albuminuria (1); allergic disease (1); Alzheimer disease (1); Anxiety (1); aortic aneurysm (1); aortic atherosclerosis (1); breast adenocarcinoma (1); breast tumors (1); carcinoma in situ (1); central nervous system diseases (1); central obesity (1); cerebrovascular diseases (1); colonic adenomas (1); colonic polyps (1).
A further 47 diseases each share a sentence with NOX1 in 1 paper.